SYT15B (synaptotagmin 15B)
Tractability: Antibody: its Gene Ontology location is reachable by antibodies, with medium confidence.
Gene: Protein-coding gene on chromosome 10 (47,744,717 to 47,763,592, reverse strand). Ensembl gene ENSG00000277758.
Subcellular location (Human Protein Atlas): Golgi apparatus
Gene Ontology:
Molecular function: calcium ion sensor activity; calcium-dependent phospholipid binding; SNARE binding
Biological process: regulation of calcium ion-dependent exocytosis; vesicle-mediated transport
Cellular component: exocytic vesicle; plasma membrane
Genetic constraint (gnomAD): Loss-of-function variants: 0 observed, 4.4 expected, observed/expected ratio (o/e) 0, 90% interval 0 to 0.68. That is too few expected variants to judge how well the gene tolerates losing a copy. Missense variants: 4 observed, 48.64 expected, observed/expected ratio (o/e) 0.0822, 90% interval 0.04 to 0.19. Synonymous variants: 0 observed, 14.75 expected, observed/expected ratio (o/e) 0, 90% interval 0 to 0.2.
Homologues: Orthologues: macaque SYT15 (96% identical), mouse Syt15 (78% identical), rat Syt15 (77% identical), tropical clawed frog syt15 (60% identical), zebrafish syt15 (38% identical). Paralogues in human: SYT15 (100% identical), SYT17 (28% identical), SYT3 (28% identical), SYT9 (28% identical), SYT6 (27% identical), SYT10 (27% identical), SYT5 (26% identical), SYT1 (25% identical), SYT2 (25% identical), SYTL4 (25% identical), SYT14 (24% identical), SYT4 (24% identical), and 19 more.